NUP62CL (nucleoporin 62 C-terminal like)
Synonyms: FLJ20130
Tractability: PROTAC: ubiquitination databases record sites on it.
Gene: Protein-coding gene on chromosome X (107,123,427 to 107,206,505, reverse strand). Ensembl gene ENSG00000198088.
Gene Ontology:
Molecular function: protein binding; structural constituent of nuclear pore
Biological process: nucleocytoplasmic transport
Cellular component: nuclear envelope; nuclear pore
Homologues: Orthologues: chimpanzee NUP62CL (99% identical), macaque NUP62CL (93% identical), pig NUP62CL (66% identical), guinea pig NUP62CL (54% identical), dog NUP62CL (52% identical), mouse Nup62cl (48% identical), rat Nup62cl (48% identical). Paralogues in human: NUP62 (55% identical).
Diseases named in the same sentence as NUP62CL in open-access papers:
NUP62CL is named in the same sentence as 4 diseases in open-access papers, as found by Europe PMC text mining. Sharing a sentence is not in itself a finding about the gene and the disease. The quoted sentences say what the papers report.
lung carcinoma (2 papers, 2018 to 2022). "Among the 363 up-regulated genes, 32 are prognostic markers in lung cancer, all of unfavorable prognosis, including LRP8, NUP62CL, FSCN1, PLCD3 or HMGA1." (PMID 36544755, 2022).
lung adenocarcinoma (1 paper, 2021). A carcinoma that arises from the lung and is characterized by the presence of malignant glandular epithelial cells. "Possibly, our study might be the first to suggest the association with cancer of the NUP62CL expression and its potential to be a biomarker in the lung adenocarcinoma prognosis." (PMID 33934535, 2021). "The Gene Set Enrichment Analysis (GSEA) between the high and the low expression data of NUP62CL was conducted to identify the significant signaling pathways activated in the Lung adenocarcinoma." (PMID 33934535, 2021). "Moreover, the key pathway of NUP62CL regulation in lung adenocarcinoma needs further validation." (PMID 33934535, 2021). "Therefore, NUP62CL may be a promising prognostic biomarker of lung adenocarcinoma." (PMID 33934535, 2021).
cancer (1 paper, 2021). A tumor composed of atypical neoplastic, often pleomorphic cells that invade other tissues. "Nonetheless, the involvement of NUP62CL in the development of cancer presently has not been indicated by any study so far." (PMID 33934535, 2021).
tumor (1 paper, 2021). "From the GEPIA database, it was found that the expression of NUP62CL was significantly higher in the tumor tissues than in the normal group." (PMID 33934535, 2021). "The total 535 tumor samples were segregated according to the NUP62CL expression into two parts as, 268 samples of high expression and 267 samples of low expression." (PMID 33934535, 2021). "Higher incidence of the expression of NUP62CL in tumor tissue than in the normal tissue was indicated by the immunohistochemistry analysis from HPA." (PMID 33934535, 2021). "Moreover the positive correlation with the NUP62CL expression in LUAD of the infiltration level of the tumor infiltrating B lymphocytes and memory CD4+ T cells was exhibited by CIBERSORT." (PMID 33934535, 2021). "Moreover, the tumor‐immunity‐interactions correlation, the mechanism involved, besides the understanding and establishing the positive role of the NUP62CL could be possible from the conclusions we drew." (PMID 33934535, 2021). "Our study established an increased NUP62CL expression in LUAD as correlating with overall survival and poor prognosis, as well as advanced clinic‐pathological aspects, such as clinical stage, tumor, node, metastasis." (PMID 33934535, 2021). "Overall, with reference to LUAD, we analyzed 22 immune cell subsets and ascertained NUP62CL significantly correlated with tumor‐infiltrating memory CD4+ T cells and tumor infiltrating B lymphocytes, primarily as potential prognostic biomarkers for progression." (PMID 33934535, 2021). "The NUP62CL regulated tumor immunology was conclusively indicated by the positive correlation with memory CD4+ T cells and the significant aspect of our study entailing the NUP62CL expression regarding the immune infiltration levels in LUAD." (PMID 33934535, 2021).